RNU6-176P (RNA, U6 small nuclear 176, pseudogene)
Gene: Small nuclear RNA gene on chromosome 1 (28,142,737 to 28,142,841, reverse strand). Ensembl gene ENSG00000253005.
Homologues: Orthologues: chimpanzee U6 (97% identical), macaque U6 (90% identical), pig U6 (82% identical), mouse Gm22078 (71% identical), guinea pig U6 (65% identical). Paralogues in human: RNU6-38P (86% identical), RNU6-480P (86% identical), RNU6-616P (85% identical), RNU6-83P (85% identical), RNU6-1005P (84% identical), RNU6-1145P (84% identical), RNU6-17P (84% identical), RNU6-18P (84% identical), RNU6-468P (84% identical), RNU6-477P (84% identical), RNU6-533P (84% identical), RNU6-774P (84% identical), and 1287 more.